LETM1 (leucine zipper and EF-hand containing transmembrane protein 1)
Description:
Plays an important role in maintenance of mitochondrial morphology and in mediating either calcium or potassium/proton antiport. Mediates proton-dependent calcium efflux from mitochondrion. Also functions as an electroneutral mitochondrial proton/potassium exchanger. Crucial for the maintenance of mitochondrial tubular networks and for the assembly of the supercomplexes of the respiratory chain. Required for the maintenance of the tubular shape and cristae organization.
Synonyms: KHE; SLC55A1; Mdm38; CONDMIM
Tractability: Antibody: UniProt predicts a signal peptide or a membrane-spanning region. PROTAC: ubiquitination databases record sites on it; its protein half-life has been measured.
Gene: Protein-coding gene on chromosome 4 (1,811,479 to 1,856,232, reverse strand). Ensembl gene ENSG00000168924.
Subcellular location: Mitochondrion inner membrane
Subcellular location (Human Protein Atlas): Mitochondria
Pathways (Reactome):
Metabolism: Complex III assembly
Signal Transduction: RHOG GTPase cycle
Transport of small molecules: Mitochondrial calcium ion transport
Gene Ontology:
Molecular function: calcium:proton antiporter activity; potassium:proton antiporter activity; protein binding; calcium ion binding; ribosome binding
Biological process: calcium export from the mitochondrion; calcium ion transport; cristae formation; inner mitochondrial membrane organization; mitochondrial calcium ion homeostasis; mitochondrial calcium ion transmembrane transport; mitochondrial potassium ion transmembrane transport; negative regulation of mitochondrial calcium ion concentration; regulation of cellular hyperosmotic salinity response; mitochondrion organization; protein hexamerization; protein homooligomerization; proton transmembrane transport
Cellular component: mitochondrial inner membrane; mitochondrion
Genetic constraint (gnomAD): Loss-of-function variants: 48 observed, 69.29 expected, observed/expected ratio (o/e) 0.69, 90% interval 0.55 to 0.88. The upper end of that interval is the gene's LOEUF score, 0.88, which puts it in group 3 of 6, group 1 being the genes least tolerant of losing a copy. Missense variants: 797 observed, 940.23 expected, observed/expected ratio (o/e) 0.85, 90% interval 0.8 to 0.9. Synonymous variants: 439 observed, 394.72 expected, observed/expected ratio (o/e) 1.11, 90% interval 1.03 to 1.2.
Homologues: Orthologues: chimpanzee LETM1 (97% identical), macaque LETM1 (94% identical), dog LETM1 (86% identical), mouse Letm1 (84% identical), guinea pig LETM1 (83% identical), pig LETM1 (81% identical), rat Letm1 (81% identical), tropical clawed frog letm1 (68% identical), zebrafish letm1 (64% identical). Paralogues in human: LETM2 (29% identical), LETMD1 (11% identical).
Diseases named in the same sentence as LETM1 in open-access papers:
LETM1 is named in the same sentence as 69 diseases in open-access papers, as found by Europe PMC text mining. Sharing a sentence is not in itself a finding about the gene and the disease. The quoted sentences say what the papers report.
Wolf-Hirschhorn syndrome (13 papers, 2014 to 2025). Wolf-Hirschhorn syndrome (WHS) is a developmental disorder characterized by typical craniofacial features, prenatal and postnatal growth impairment, intellectual disability, severe delayed psychomotor development, seizures, and hypotonia. "The mitochondrial inner membrane protein Leucine zipper-EF-hand containing Transmembrane Protein 1 (Letm1), implicated in Wolf-Hirschhorn Syndrome, is essential for mitochondrial function." (PMID 40849623, 2025). "Letm1, a mitochondrial inner-membrane protein, was initially identified as a gene associated with the Wolf-Hirschhorn Syndrome (WHS), linked to the deletion of the short arm of chromosome 4." (PMID 40849623, 2025). "Letm1 is historically recognized as a mitochondrial potassium-proton exchanger implicated in Wolf-Hirschhorn Syndrome." (PMID 40849623, 2025). "LETM1 is located in the inner mitochondrial membrane and its deficiency is known to lead to Wolf-Hirschhorn syndrome." (PMID 33110478, 2020). "LETM1, which was initially discovered as an excellent candidate gene for Wolf-Hirschhorn syndrome, encodes a member of the EF-hand family of Ca(2+)-binding proteins, which contains two EF hands, a transmembrane domain, a leucine zipper, and several coiled-coil domains." (PMID 24689060, 2014). "LETM1 is associated with the Wolf-Hirschhorn Syndrome (WHS), a complex multigenic disease caused by haploinsufficiency of the WHSCR 1 and 2 regions on chromosome 4." (PMID 24616706, 2014). "The mitochondrial cation exchanger LETM1 sparks interest because of its pathophysiological role in seizures in the Wolf Hirschhorn Syndrome (WHS)." (PMID 35697381, 2022). "The LETM1 gene was first identified as one of the genes deleted in Wolf-Hirschhorn syndrome, which is characterized by a contiguous gene disorder resulting from a hemizygous deletion on chromosome 4, and encodes the human homolog of yeast protein Mdm38p." (PMID 24689060, 2014). "LETM1 haploinsufficiency correlates with seizures in the Wolf Hirschhorn Syndrome (WHS)." (PMID 35697381, 2022). "The CHE is encoded by the mitochondrial protein LETM1, although it was first identified as a KHE responsible for mitochondrial dysmorphism in patients with the Wolf-Hirschhorn syndrome." (PMID 33041851, 2020). "The significance of LETM1 to mitochondrial Ca2+ regulation is evident from Wolf-Hirschhorn syndrome patients that harbor a haplodeficiency in LETM1 expression, leading to dysfunctional mitochondrial Ca2+ handling and from numerous types of cancer cells that show an upregulation of LETM1 expression." (PMID 30642051, 2019). "The Letm1 gene was originally identified as one of the genes deleted in patients afflicted with the Wolf-Hirschhorn Syndrome (WHS), a contiguous gene deletion disorder marked by severe growth and intellectual disability, hypotonia, and seizures." (PMID 33815143, 2021). "Two critical regions are involved in the Wolf-Hirschhorn syndrome critical region (WHSCR): WHSCR1 (WHSC1 and WHSC2 genes included) and WHSCR2 (WHSC1 and LETM1 genes included)." (PMID 32566663, 2020). "Leucine zipper EF-hand containing transmembrane protein 1 (LETM1), which was first discovered in patients with Wolf-Hirschhorn syndrome (WHS), has been reported to enhance mitochondrial Ca2+ transport and cell proliferation." (PMID 27556512, 2016).
epilepsy (10 papers, 2009 to 2025). A brain disorder characterized by episodes of abnormally increased neuronal discharge resulting in transient episodes of sensory or motor neurological dysfunction, or psychic dysfunction. "LETM1 is proposed to be associated with epilepsy and neuromuscular features of WHS." (PMID 36055214, 2022). "Future studies may integrate GFAP scoring with detailed gene-level analyses to better understand how specific genes within the 4p16.3 region—such as NSD2 (associated with developmental delay), LETM1 (epilepsy), or CPLX1 (synaptic function)—modulate individual trajectories." (PMID 40725476, 2025). "Monoallelic LETM1 deletion has been suggested to be responsible for epilepsy and neuromuscular features in WHS." (PMID 36055214, 2022). "This is consistent with a reduced expression of LETM1 in patients with temporal lobe epilepsy and in a rat pilocarpine-induced epilepsy model, exhibiting mitochondrial swelling, early onset of the first seizure, and increased seizure frequency and duration." (PMID 33815143, 2021). "Given the role of LETM1 in the formation of respiratory supercomplexes and protein import via interactions with BCS1L and MRPL36, it is likely that this aspect of LETM1-depedent regulation also plays a role in the effects of LETM1-KD in epilepsy." (PMID 33815143, 2021). "In the present study, while the LETM1 gene is deleted in both cases only the first patient presents epilepsy." (PMID 33627176, 2021). "Interestingly, however, LETM1-KD in the epilepsy model also decreased the expression of mitochondrial cytochrome b, a component of complex III." (PMID 33815143, 2021). "LETM1 has been found to be deleted in Wolf-Hirschorn syndrome (WHS), a complex congenital syndrome characterized by microcephaly, growth and mental retardation, seizures, epilepsy and other associated symptoms." (PMID 19421406, 2009). "Indeed, the current LETM1 cohort presented with hypotonia and epilepsy." (PMID 36055214, 2022). "The mechanism by which LETM1 expression regulates the progression of epilepsy or ALS is unknown." (PMID 33815143, 2021). "Candidate genes for epilepsy phenotype were identified in these regions, such as Wolf-Hirschhorn Syndrome Candidate 1 gene (WHSC1, current name Nuclear Receptor Binding SET Domain Protein 2 - NDS2) and Leucine Zipper And EF-Hand Containing Transmembrane Protein 1 gene (LETM1), respectively." (PMID 33987468, 2020).
lung carcinoma (6 papers, 2010 to 2024). "In the current study, we demonstrated a molercular role of LETM1 complex which involve in the mitochondria-ER association and facilitated the miochondrial regulation in lung cancer cells." (PMID 35680871, 2022). "The in vitro findings were also reproduced in K-rasLA1 murine lung cancer model treated adenovirus-LETM1 via aerosol, suggesting that loss of ATP level in adenovirus-LETM1 infected cells causes AMPK activation." (PMID 20824095, 2010). "Indeed, both levels of LETM1 and PINK1 were elevated in the human lung carcinoma implicating for the association of LETM1-mitophagy and lung cancer progression and development." (PMID 35680871, 2022). "Therefore, this study was designed to investigate the tumor suppressor function of LETM1 and clarify the mechanism underlying tumor growth inhibition in lung cancer model." (PMID 20824095, 2010). "LETM1 has also been shown to be overexpressed in different human cancer tissues, including lung cancer." (PMID 35680871, 2022). "In this study, we describe the expression of LETM1 in lung cancer cells as a reliable marker of poor prognosis for patients with NSCLC." (PMID 31500591, 2019). "The phenomenon suggests that dysregulation of LETM1 has far-reaching influence in the dysfunction of lung cancer cells." (PMID 31500591, 2019). "Theses results demonstrated that adenovirus-LETM1 suppressed lung cancer cell growth in vitro and in vivo." (PMID 20824095, 2010). "Our results clearly indicated that adenovirus-LETM1 suppressed cancer cell proliferation in the lungs of human lung cancer model mice." (PMID 20824095, 2010). "In our study, we showed that LETM1 overexpression decreased specific mitochondrial protein cytochrome c oxidase subunit IV resulting in a reduction of mitochondrial ATP level in lung cancer cells." (PMID 20824095, 2010). "To investigate the effect of adenovirus-LETM1 on the growth of lung cancer, we examined such potential anti-tumor effects in K-rasLA1 mice." (PMID 20824095, 2010). "In this study, we addressed this question by studying in the effect of adenovirus-mediated LETM1 in the lung cancer cell and lung cancer model mice." (PMID 20824095, 2010). "LETM1/HSPA5 axis or HSPA5-LETM1 interaction was revealed to play roles in lung cancer progression." (PMID 37275848, 2023). "In addition, LETM1 was shown to be overexpressed in different human cancers, including lung cancer (PMID: 31500591, 2024095)." (PMID 35680871, 2022). "Fragmented mitochondria have been found in lung cancer cells with LETM1 overexpression." (PMID 35680871, 2022). "The effects of LETM1 on lung cancer growth and AMPK related signals were evaluated." (PMID 20824095, 2010). "Our results support the hypothesis that LETM1 may function as a tumor suppressor gene for lung cancer therapy as well as prevention." (PMID 20824095, 2010). "Adenovirus-mediated overexpression of LETM1 could induce destruction of mitochondria of lung cancer cells through depleting ATP and AMPK activation." (PMID 20824095, 2010). "Moreover, some controversies persist regarding the role of LETM1 in lung cancer cells." (PMID 31500591, 2019). "Therefore, understanding the role of LETM1 may be important in developing effective therapeutics for lung cancer." (PMID 20824095, 2010). "Taken together, these observations support the notion that the complex formation of LETM1/GRP75/GRP78 might be an important step in MAM formation and mitophagy, thus regulating mitochondrial quality control in lung cancer." (PMID 35680871, 2022). "LETM1 contributes to cancer cell proliferation and invasion via the PI3K/Akt signaling pathway and has been identified as a potential biomarker to predict the prognosis of gastric cancer and lung cancer." (PMID 34604236, 2021).
microcephaly (4 papers, 2009 to 2022). A congenital or acquired developmental disorder in which the circumference of the head is smaller than normal for the person's age and sex. "We confined the region of susceptibility for microcephaly and seizures to a 330 kb sized region that encompassed seven candidate genes (LETM1, FGFR3, WHSC1, NELFA, C4orf48, NAT8LI, and POLN)." (PMID 29721507, 2018).
non-small cell lung carcinoma (4 papers, 2010 to 2021). A group of at least three distinct histological types of lung cancer, including non-small cell squamous cell carcinoma, adenocarcinoma, and large cell carcinoma. "Additionally, in vivo effects of LETM1 were evaluated on K-rasLA1 mice, human non-small cell lung cancer model mice, by delivering the LETM1 via aerosol through nose-only inhalation system." (PMID 20824095, 2010). "Leucine zipper-EF-hand-containing transmembrane protein 1 (LETM1), a mitochondrial endosomal protein, is highly expressed in many human malignancies, such as gastric adenocarcinoma, non-small cell lung carcinoma and colorectal adenocarcinoma, and has a close relationship with poor prognosis." (PMID 34605738, 2021). "Given that loss of LETM1 suppresses ATP production, enhances ROS, and inhibits cell proliferation, it is no surprise the overexpression of LETM1 has been found in many cancers, including ovarian, rectal, stomach, esophagus, breast, colon, and lung non-small cell carcinoma." (PMID 32455637, 2020).
diabetes (3 papers, 2015 to 2022). "Other implications of LETM1 impairment in genetic diseases include temporal lobe epilepsy, diabetes, and obesity." (PMID 36055214, 2022). "The associated region and its close neighbourhood harbours interesting candidate genes such as LETM1 and GAPDH that are important in glucose metabolism and have previously been implicated in the aetiology of diabetes mellitus." (PMID 25970163, 2015).
liver cancer (3 papers, 2020 to 2024). An epithelial or non-epithelial malignant neoplasm that arises from the liver. "LETM1 controls both autophagy and apoptosis in liver cancer, with elevated levels found in hepatocellular carcinoma tissue, cell lines, and linked to a negative outlook." (PMID 39650649, 2024). "Depletion of LETM1 triggers apoptosis, autophagy, and hindrance of growth in liver cancer cell lines." (PMID 39650649, 2024). "In addition, knockdown of LETM1 inhibited proliferation and enhanced apoptosis and autophagy in the Huh 7 and QGY-7701 liver cancer cell lines." (PMID 33552978, 2020). "100μmol/L luteolin inhibits the proliferation of liver cancer cells by down-regulating the miRNA expression of the proliferation-related genes LETM1, URG11, PICK1, and CyclinD1 in HepG2 liver cancer cells, suggesting that luteolin may inhibit cell proliferation." (PMID 37151401, 2023).
lymph node metastasis (3 papers, 2014 to 2019). "In triple-negative breast cancer, the LETM1 expression is significantly associated with histological grade, clinical stage, and lymph node metastasis." (PMID 31500591, 2019). "On the contrary, our results revealed that LETM1 expression is significantly associated with lymph node metastasis and advanced clinical stage." (PMID 31500591, 2019). "Taken together, our findings demonstrate that LETM1 plays an important role in the progression of HNSCC, and high levels of LETM1 protein are significantly associated with the presence of lymph node metastasis, advanced stage, poor differentiation, and shortened survival of patients with HNSCC." (PMID 24689060, 2014). "Our studies show that expression of LETM1 is significantly correlated with the lymph node metastasis (p = 0.003) and the clinical stage (p = 0.005) of NSCLC." (PMID 31500591, 2019). "Further, the univariate Cox regression analysis show that following factors are significant prognostic factors of poor OS: pT stage (p = 0.002), lymph node metastasis (p = 0.002), and LETM1 expression (p = 0.006)." (PMID 31500591, 2019). "The multivariate Cox regression analysis show that pT stage (p = 0.005), lymph node metastasis (p = 0.012), and LETM1 expression (p = 0.008) are adverse independent poor prognostic predictor of NSCLC in terms of OS." (PMID 31500591, 2019). "LETM1 expression is significantly correlated with the status of lymph node metastasis (p = 0.003) and clinical stage (p = 0.005) (Pearson’s χ2 test)." (PMID 31500591, 2019). "Remarkably, the lymphovascular invasion (LVI) and lymph node metastasis (LNM) were more frequently observed in patients with PTC showing moderate to strong LETM1 staining intensities." (PMID 27556512, 2016). "LETM1 overexpression significantly correlated with poor differentiation, advanced tumor stage, presence of lymph node metastasis, absence of chemoradiotherapy, and shortened survival time in patients with HNSCC." (PMID 24689060, 2014). "LETM1 overexpression correlated with poor differentiation, presence of lymph node metastasis, advanced stage, absence of chemoradiotherapy, and 5-year disease-free survival and overall survival rates in HNSCC." (PMID 24689060, 2014). "Similarly, we found that the strongly positive rate of LETM1 protein was higher in HNSCC with lymph node metastasis (72.2%, 96/133) than in cases with nonmetastasis (44.2%, 19/43) (P = 0.001)." (PMID 24689060, 2014).
ovarian carcinoma (3 papers, 2020 to 2023). A malignant neoplasm originating from the surface ovarian epithelium. "In addition, many m6A-related factors such as YTHDF2, LETM1, METL3 and ALKBH5 have also been confirmed to be associated with the malignancy of ovarian cancer." (PMID 37005667, 2023). "For example, in ovarian cancer, lncRNA RHPN1-AS1 acts as a competing endogenous RNA (ceRNA) against miR-596 and upregulates LETM1, promoting tumorigenesis and metastasis." (PMID 33381557, 2020).
bladder cancer (2 papers, 2020 to 2021). "For example, Huang et al18 reported that LETM1 promotes the proliferation and invasion of bladder cancer cells." (PMID 33314691, 2021). "It has been demonstrated that knockdown of LETM1 suppresses the proliferation and invasion of bladder cancer cells, indicating an oncogenic role of LETM1 in cancer." (PMID 32163372, 2020). "Indeed, a study by Huang et al18 showed that suppression of LETM1 inhibited the proliferation of bladder cancer cells, consistent with our results demonstrating that LETM1 down‐regulation blocked CRC cell proliferation." (PMID 33314691, 2021).
Cachexia (2 papers, 2020 to 2024). Severe weight loss, wasting of muscle, loss of appetite, and general debility related to a chronic disease. "We examined the amount of LETM1, a structural protein of mitochondria, in the myocardium of the cachexia model and found that it was decreased." (PMID 33110478, 2020).
colorectal cancer (2 papers, 2021 to 2024). A primary or metastatic malignant neoplasm that affects the colon or rectum. "Although LETM1 is known to be associated with poor prognosis in colorectal cancer (CRC), its roles in autophagic cell death in CRC have not been explored." (PMID 33314691, 2021). "In addition, the results of IF revealed that LETM1 co‐localized with cyclin A2 and CDK2 in colorectal cancer cells." (PMID 33314691, 2021).
developmental delay (2 papers, 2022 to 2025). "LETM1 c.2220G>C (p.∗740Tyrext26) was identified in several subjects from F2 and F7 with developmental delay, walking difficulties, and seizures." (PMID 36055214, 2022).